MIR4682 (microRNA 4682)
Synonyms: hsa-mir-4682
Gene: MicroRNA gene on chromosome 10 (119,958,513 to 119,958,592, forward strand). Ensembl gene ENSG00000265370.
Homologues: Orthologues: chimpanzee MIR4682 (100% identical).